HDAC3 (histone deacetylase 3)
Diseases named in the same sentence as HDAC3 in open-access papers (continued):
Sharing a sentence is not in itself a finding about the gene and the disease.
cardiac hypertrophy (15 papers, 2010 to 2025). "Cardiomyocyte-specific KO of HDAC3 with αMHC-Cre in mice caused cardiac hypertrophy, elevated myocardial triglyceride content, and lethal heart failure." (PMID 38983721, 2024). "Cardiac-specific inactivation of Hdac3 gene caused cardiac hypertrophy and alteration in fatty acid metabolism." (PMID 36523510, 2022). "HDAC3 deficiency in cardiomyocytes causes severe cardiac hypertrophy at early age and excessive accumulation of triglycerides, which is accompanied by upregulation of genes related to energy metabolism." (PMID 31532577, 2019). "Cardiac specific loss of HDAC1 and HDAC2 for example results in cardiac arrhythmias and heart failure, while loss of HDAC3 function leads to cardiac hypertrophy." (PMID 23341106, 2013). "For example, both cardiomyocyte-specific KO of HDAC3 and cardiomyocyte-specific transgenic OE of HDAC3 can lead to cardiac hypertrophy." (PMID 38983721, 2024). "HDAC3 enzyme is involved in the repressive activities of NCoR1, and depletion of HDAC3 in cardiomyocytes results in severe cardiac hypertrophy at an early stage." (PMID 37674539, 2023). "Loss of HDAC3 (histone deacetylase 3) and the activity of transcription factor MEF2 (myocyte enhancer factor-2) has been shown to be associated to cardiac hypertrophy." (PMID 37686151, 2023). "Cardiomyocyte‐specific HDAC3 knockout leads to cardiac hypertrophy and imbalance of lipid disposal in mouse heart." (PMID 31532577, 2019). "For example, HDAC2 promotes cardiac hypertrophy, and cardiac-specific deletion of HDAC3 in mice leads to cardiac hypertrophy and excessive myocardial lipid accumulation." (PMID 30115891, 2018). "Conditional deletion of Hdac3 in cardiomyocytes elevated expression of Ppar-alpha target genes and increased fatty-acid-induced myocardial lipid accumulation and cardiac hypertrophy." (PMID 20628553, 2010). "Both studies suggest that HDAC3 is critical in regulating cardiac hypertrophy and lipid metabolism." (PMID 38983721, 2024). "HDAC3 aggravates cardiac hypertrophy by deacetylating cardiac myosin heavy chain (MHC) isoforms." (PMID 37143582, 2023). "HDAC3 has been involved in developing cardiac hypertrophy in mice." (PMID 36523510, 2022). "Moreover, HDAC3 deletion induces cardiac hypertrophy, and global deletion of HDAC3 results in embryonic lethality at E9.5 in the heart, whereas its inhibition prevents type 1 diabetic cardiomyopathy via epigenetic regulation of the DUSP5–ERK1/2 pathway." (PMID 33736642, 2021). "Therefore, NCoR1 works more likely through class IIa HDACs instead of HDAC3 to affect cardiac hypertrophy." (PMID 31532577, 2019). "Finally, HDAC3 expression and activity increase during hypertrophy whereas a decreased binding of HDAC3 to myofibrils is observed in PE-induced hypertrophy in neonatal rat cardiomyocytes that increases the acetylation of CapZβ1 at lysine 199 and alters myofibril growth during cardiac hypertrophy." (PMID 36009379, 2022). "Unlike Hdac2-Tg mice, Hdac3-Tg mice do not exhibit cardiac hypertrophy, which indicates that Hdac3 is a unique regulator of cardiac cell proliferation." (PMID 40660005, 2025). "Cardiomyocyte-specific transgenic OE of HDAC3 with αMHC displayed ventricular myocardium thickening at birth due to cardiomyocyte hyperplasia, but there was no further increase in cardiac hypertrophy in adults under isoproterenol stimulation compared with WT." (PMID 38983721, 2024). "In addition, in cardiac-specific HDAC3 knockout mice, HDAC3 cooperates with SMRT/n-CoR to a reduce histone acetylation in the vicinity of myocyte enhancer factor 2 (MEF2), resulting in abnormal energy metabolism and cardiac hypertrophy." (PMID 40710369, 2025). "HDAC3 increases postnatal cardiac myocyte proliferation but is not involved in cardiac hypertrophy." (PMID 35126818, 2022).
Huntington disease (15 papers, 2011 to 2025). Huntington disease (HD) is a rare neurodegenerative disorder of the central nervous system characterized by unwanted choreatic movements, behavioral and psychiatric disturbances and dementia. "The role of HDAC3 is known to be associated with several life-threatening diseases such as cancer, inflammatory diseases, cardiovascular diseases, neurodegenerative diseases, learning and memory dysfunctions, Huntington’s disease (HD), and diabetes." (PMID 37446052, 2023). "HDAC3 translocated from the cytoplasm to the nuclei by day 5; an observation consistent with the earlier research where HDAC3 localized to the nuclei in dying cortical neurons in an in vivo Huntington’s disease model." (PMID 36012190, 2022). "Recent evidence has shown that HDAC3 is involved in I/R-induced brain injury and poststroke recovery and participates in neurodegenerative diseases such as Huntington’s disease or Parkinson’s disease." (PMID 35251047, 2022). "HDAC3 has also been shown to be toxic to neurons in vitro, and in models of degenerative disease such as Huntington’s disease, spinocerebellar ataxia type 7, and Friedrich’s ataxia." (PMID 25261965, 2014). "A drug administration regimen using HDACi 4b dissolved in drinking water was used in the previous proof of concept study, casting doubt on the validation of CNS HDAC3 inhibition as a target for the treatment of Huntington’s disease." (PMID 22973455, 2012). "Moreover, administration of the HDAC3 inhibitor RGFP966 to a Huntington’s disease mouse model decreased repeat expansion." (PMID 34494094, 2022). "The benefits for Huntington’s disease may also be related to macrophage migration inhibitory factor (Mif), which could be downregulated by selective HDAC3 inhibitor in mice." (PMID 29498635, 2018). "Moreover, selective HDAC3 inhibitors can impede Huntington’s disease-related gene expansion, and thereby protect against cognitive decline." (PMID 29498635, 2018). "HDAC3 is widely expressed in a variety of cells, including oligodendrocytes responsible for myelination and striatum for Huntington disease." (PMID 27729849, 2016). "Similarly, HDAC3 mediates toxicity in a Caenorhabditis elegans model of Huntington's Disease as well as in in vitro models of neuronal oxidative death." (PMID 22582024, 2011). "c-Abl also mediates neuronal cell death via the interaction of HDAC3 and c-Fos in mouse models of Huntington’s disease, where c-Fos expression is selectively reduced in the striatum and its forced expression has been shown to protect against the neurotoxic effects of activated c-Abl and HDAC3." (PMID 37626851, 2023). "More recent studies demonstrate that a selective inhibitor of HDAC3 (selective inhibitor RGFP966) suppressed striatal CAG repeat expansions and prevented cognitive defects in Huntington’s disease mice." (PMID 40558500, 2025). "This review will discuss evidence supporting the involvement of HDAC1 and HDAC3 in polyglutamine disorders, including Huntington’s disease, and the use of HDAC1- and HDAC3-selective HDAC inhibitors as therapeutic intervention for these disorders." (PMID 24865773, 2014).
pulmonary fibrosis (14 papers, 2020 to 2026). Chronic progressive interstitial lung disorder characterized by the replacement of the lung tissue by connective tissue, leading to progressive dyspnea, respiratory failure, or right heart failure. "We verified that HDAC3 deficiency in AT2 cells alleviated BLM-induced pulmonary fibrosis in mice and TGF-β1-induced EMT in vitro, as evidenced by increased E-cadherin expression and decreased N-cadherin and vimentin expression." (PMID 37951958, 2023). "To further confirm the potential roles of HDAC3 in mice with pulmonary fibrosis, we next generated AT2 cell-specific HDAC3-deficient mice by genetic engineering." (PMID 37951958, 2023). "Moreover, HDAC3 deficiency in AT2 cells prevented mice from developing BLM-induced pulmonary fibrosis, characterized by a marked reduction of EMT in AT2 cells." (PMID 38474021, 2024). "Additionally, numerous studies have confirmed that Hdac3 is a risk gene exacerbating pulmonary fibrosis." (PMID 39224841, 2024). "Collectively, these data suggested that HDAC3 deficiency in AT2 cells could inhibit BLM-induced pulmonary fibrosis by suppressing EMT." (PMID 37951958, 2023). "Moreover, HDAC3 deficiency in AT2 cells prevented mice from developing BLM-induced pulmonary fibrosis, which was accompanied by a marked reduction of EMT in AT2 cells from murine lung tissues." (PMID 37951958, 2023). "Therefore, the aim of this project was to determine the influence of HDAC3 on chromatin remodeling and gene expression associated with idiopathic pulmonary fibrosis." (PMID 37048093, 2023). "In 2021, it was additionally established that the upregulation of HDAC3 can result in the suppression of nuclear factor erythroid 2–related factor 2 (Nrf2), a regulator of cellular antioxidative responses, which is linked to the development of pulmonary fibrosis." (PMID 39766311, 2024). "Upregulation of Histone deacetylase 3 (HDAC3) in pulmonary fibrosis can lead to NRF2 inhibition, and by selectively inhibiting HDAC3 (e.g., using the drug RGFP966), the inhibitory effect on NRF2 can be reduced." (PMID 40258841, 2025). "In bleomycin-induced pulmonary fibrosis mice model, HDAC3 promoted EMT, inflammation, and pulmonary fibrosis development by activating STAT1 signaling." (PMID 38641226, 2024). "The effective involvement of HDAC3 in EMT-dependent fibrosis in lung was demonstrated by the use of HDAC3 siRNA that alleviated BLM-induced pulmonary fibrosis in mice." (PMID 38474021, 2024). "Since fibroblast migration is considered a critical contributor to lung fibrosis, it was recently demonstrated that HDAC3-miR224- Forkhead Box A1 (FOXA1) axis effectively regulated the migration and invasion of fibroblast cells under hypoxia." (PMID 38474021, 2024). "Under BLM stimulation, HDAC3-CKO mice showed significantly attenuated pulmonary fibrosis and decreased Ashcroft score for fibrosis, as illustrated by H&E staining, Masson’s trichrome staining, and PSR staining." (PMID 37951958, 2023). "This study demonstrated that the activation of the TGF-β1/SMAD3 signaling pathway was directly responsible for the up-regulation of HDAC3 expression in pulmonary fibrosis." (PMID 37951958, 2023). "In view of the pivotal role of HDAC3 in regulating EMT in pulmonary fibrosis, we investigated the possible mechanism by which HDAC3 regulates EMT." (PMID 37951958, 2023). "Next, to confirm the role of HDAC3 on EMT in pulmonary fibrosis, we evaluated the expression of fibrotic markers and EMT-related markers." (PMID 37951958, 2023). "In doing so, we intended to elucidate the mechanism by which HDAC3 accelerates pulmonary fibrosis progression." (PMID 35804191, 2022). "Lastly, we found this mechanism to be valid in an in vivo system; HDAC3 siRNA administration inhibited bleomycin-induced pulmonary fibrosis in mice." (PMID 35804191, 2022).
pulmonary fibrosis (continued). "Similar to the effects of HDAC3 inhibitor, selective inhibition of Hdac8 was also shown to ameliorate bleomycin-induced lung fibrosis in mice through the reduction of ECM synthesis." (PMID 35626663, 2022). "Given that several studies have used siRNAs against target genes to evaluate their effects on pulmonary fibrosis, we intratracheally injected HDAC3 siRNA into bleomycin-induced model mice to assess the effect of HDAC3 on pulmonary fibrosis." (PMID 35804191, 2022). "Further, HDAC2 and HDAC3 have been observed to be upregulated in various rodent models of pulmonary fibrosis, with predominant localisation in fibrotic lesions and lung fibroblasts." (PMID 35626663, 2022). "HE and Masson staining results showed that silencing HDAC3 improved the condition of inflammation around the alveoli in mice, and pulmonary fibrosis was alleviated after silencing HDAC3." (PMID 33343379, 2020). "We further provided evidence that HDAC3 inhibited the expression of miR-19a-3p to regulate pulmonary fibrosis." (PMID 33343379, 2020). "Although histone deacetylase 3 (HDAC3) has been implicated in acute lung injury and pulmonary fibrosis, its role in hypoxia-induced PAH remains unclear." (PMID 41543632, 2026). "Recently, a number of studies have focused on HDAC3 with regard to pulmonary fibrosis." (PMID 39766311, 2024). "Overall, these data showed that administration of the selective HDAC3 inhibitor RGFP966 may serve as a promising therapeutic strategy against pulmonary fibrosis in clinical practice." (PMID 37951958, 2023). "Based on these data, we propose that HDAC3 may be a potential therapeutic target for the prevention of pulmonary fibrosis." (PMID 37951958, 2023). "The mechanistic activity of HDAC3 in pulmonary fibrosis and EMT was also explored." (PMID 37951958, 2023). "Next, we further investigated the role of HDAC3 in pulmonary fibrosis in mice." (PMID 37951958, 2023). "Taken together, our data indicate that in addition to increased HDAC3 in AT2 cells contributing to pulmonary fibrosis, the increased HDAC3 in fibroblasts may also play an important role in the pathogenesis of pulmonary fibrosis." (PMID 37951958, 2023). "Based on these previous studies, we considered whether HDAC3 is highly expressed and functional in M2 macrophages in pulmonary fibrosis." (PMID 37951958, 2023). "To examine whether inhibition of HDAC3 is effective in regulating lung fibrosis, we established a mouse pulmonary fibrosis model in 7-week-old male mice by intratracheal instillation of bleomycin." (PMID 35804191, 2022). "HDAC3 siRNA administration alleviated bleomycin-induced pulmonary fibrosis in mice." (PMID 35804191, 2022). "Thus, our study offers an effective molecular target for pulmonary fibrosis treatment by identifying the role of HDAC3 in alveolar EMT and fibroblast migration and invasion under hypoxic conditions." (PMID 35804191, 2022). "Of note, delivery of Hdac3-targeting siRNA to RA-ILD mice attenuated lung fibrosis in mice in vivo." (PMID 35626663, 2022). "Collectively, these results indicate that inhibition of HDAC3 may suppress pulmonary fibrosis in mice through inhibition of EMT in the bleomycin-induced fibrosis model." (PMID 35804191, 2022). "Although these findings are similar to those in our study in that all indicate that HDAC3 acts as a profibrotic factor in pulmonary fibrosis, our study differs in that we focused on the finding that HDAC3 promotes pulmonary fibrosis by accelerating hypoxia-induced EMT." (PMID 35804191, 2022). "Under hypoxic conditions, HDAC3 has been shown to exacerbate pulmonary fibrosis by promoting epithelial–mesenchymal transition in alveolar epithelial cells, but whether HDAC3 inhibition can attenuate hPASMC proliferation and cytokine dysregulation in hypoxia has not been established." (PMID 41543632, 2026). "Therefore, targeted inhibition of HDAC3 in AT2 cells may provide a new therapeutic opportunity for the prevention of pulmonary fibrosis." (PMID 37951958, 2023).
pulmonary fibrosis (continued). "Therefore, we propose that HDAC3 deletion in AT2 cells may play a role in reducing pulmonary fibrosis." (PMID 37951958, 2023). "RGFP966 may also alleviate pulmonary fibrosis by inhibiting HDAC3 expression in fibroblasts." (PMID 37951958, 2023). "Thus, it is reasonable to suggest that HDAC3 may accelerate pulmonary fibrosis progression under hypoxic conditions by enhancing EMT in alveolar cells through the regulation of miR-224 and FOXA1." (PMID 35804191, 2022). "In this study, we confirmed high expression of HDAC3 in lung tissues from patients with IPF, as well as mice with BLM-induced pulmonary fibrosis, and cellular fibrosis models." (PMID 37951958, 2023). "Recent data showed that HDAC3 promotes EMT and fibroblast migration under hypoxic conditions in A549 cells and HDAC3 inhibition results in the acetylation and degradation of NICD1, thereby alleviating pulmonary fibrosis." (PMID 37951958, 2023). "Consistent with this, intraperitoneal administration of the selective HDAC3 inhibitor, RGFP966, protected against BLM-induced pulmonary fibrosis in mice by targeting EMT in AT2 cells." (PMID 37951958, 2023). "Collectively, these data indicate that HDAC3 is highly expressed and plays a role in AT2 cells in pulmonary fibrosis." (PMID 37951958, 2023). "TGF-β1/SMAD3 directly promoted the transcription of HDAC3, which aggravated EMT in AT2 and pulmonary fibrosis in mice via deacetylation of GATA3 and inhibition of its degradation." (PMID 37951958, 2023). "More importantly, HDAC3 played a pivotal role in mediating EMT in AT2 cells and pulmonary fibrosis by deacetylating GATA3 and inhibiting its degradation." (PMID 37951958, 2023). "Until now, most of the agents developed have selectivity for HDAC3, HDAC6 and HDAC8 and have been or are still currently evaluated in preclinical studies for cancer and lung fibrosis." (PMID 35626663, 2022). "On the other hand, selective inhibition of HDAC3, HDAC6 or HDAC8 has recently been demonstrated to exert remarkable therapeutic effects in the bleomycin mouse model of lung fibrosis." (PMID 35626663, 2022). "To test whether HDAC3 regulates the migration and invasion of human fibroblast cells under hypoxic conditions, we performed a scratch wound healing assay using diseased human lung fibroblasts from patients with idiopathic pulmonary fibrosis (DHLF-IPF cells) and MRC-5 human lung fibroblast cells." (PMID 35804191, 2022). "Taken together, aberrant overexpression of HDAC3 and its exerted suppression of NRF2 plays a pivotal role in lung fibrosis, including IPF, which can be attenuated by selective inhibition of HDAC3." (PMID 35626663, 2022). "Firstly, we measured the expression of HDAC3 and interleukin 17 receptor A (IL17RA) in lung tissue samples from normal controls, idiopathic pulmonary fibrosis (IPF) patients, and RA-ILD patients." (PMID 33343379, 2020). "In addition, HDAC3 was upregulated in alveolar epithelial type 2 (AT2) cells from patients with IPF, and in AT2 cells from mice with BLM-induced pulmonary fibrosis." (PMID 38474021, 2024). "In the present study, we found that HDAC3 was upregulated in lung tissues and AT2 cells from patients with IPF, and consistently detectable in lung tissues and AT2 cells from mice with BLM-induced pulmonary fibrosis." (PMID 37951958, 2023). "This suggests that HDAC3 may mediate EMT following damage to AECs in ALI, and may be a target for the inhibition of pulmonary fibrosis." (PMID 37175583, 2023). "Given the findings above, we speculate that HDAC3 may serve as a novel target for therapeutic intervention in bleomycin-induced EMT and pulmonary fibrosis." (PMID 37951958, 2023). "Moreover, AT2-specific deletion of HDAC3 or intraperitoneal injection of the selective HDAC3 inhibitor, RGFP966, significantly alleviated EMT in mice with BLM-induced pulmonary fibrosis." (PMID 37951958, 2023).
pulmonary fibrosis (continued). "Taken together, these results suggest that HDAC3 induces miR-224 expression to drive alveolar EMT through FOXA1 downregulation under hypoxic conditions, which may accelerate pulmonary fibrosis." (PMID 35804191, 2022). "Finally, we found that intraperitoneal administration of RGFP966, a selective inhibitor of HDAC3, could prevent mice from BLM-induced pulmonary fibrosis and EMT." (PMID 37951958, 2023).